TRPC3 (transient receptor potential cation channel subfamily C member 3)
Diseases named in the same sentence as TRPC3 in open-access papers (continued):
Sharing a sentence is not in itself a finding about the gene and the disease.
Alzheimer disease (4 papers, 2022 to 2025). A progressive, neurodegenerative disease characterized by loss of function and death of nerve cells in several areas of the brain leading to loss of cognitive function such as memory and language. "In the brain, it is involved in the pathogenesis of Alzheimer’s disease, where Aβ peptides, which are linked to the development of Alzheimer’s disease, correlate with TRPC3-dependent calcium influx, leading to neurotoxicity." (PMID 39108834, 2024).
pancreatic cancer (4 papers, 2018 to 2022). "TRPC3 over-activation might manifest in the disturbance of the cellular metabolism in pancreatic tumors, but a functional test with genetically engineered PAAD cells to establish isogenic TRPC3 activation conditions similar as performed previously are needed to test this hypothesis." (PMID 35330477, 2022). "The prediction model based on MCOLN1, PKD1, TRPC3, and TPRC7 can also predict the prognosis of pancreatic cancer." (PMID 35898870, 2022). "Sensory ion channels TRPC3 and TRPC7 could be the potential therapeutic targets in pancreatic cancer and TRPC3 might be involved in dysregulating mitochondrial functions during PAAD genesis." (PMID 35330477, 2022).
Sepsis (4 papers, 2017 to 2024). Sepsis is defined as life-threatening organ dysfunction caused by a dysregulated host response to infection. "Administering a Pyr10 inhibitor to block TRPC3 channel alleviated the development of LPS-induced sepsis in mice by reducing the activation of several pro-inflammatory genes, including PTGS2, TNFA, IL-1B, and IL-6." (PMID 38731999, 2024). "For instance, TRPC3 blockade has shown promise as a therapeutic intervention in mitigating sepsis development, while the interaction between TRPC5 and TRPC4 contributes to leukocyte accumulation and the release of inflammatory mediators." (PMID 38731999, 2024). "In THP-1, Lipin-1-derived DAGs activate TRPC3 on the inner membrane of ER cells during LPS activation, and blockade of TRPC3 activity ameliorated the development of LPS-driven inflammation and sepsis in animal models." (PMID 37404813, 2023). "Our work introduces the concept that intracellular, lipid-activated TRPC3 participates in Ca2+ signaling during LPS-driven inflammation and sepsis development." (PMID 34757442, 2021). "We demonstrate that TRPC3 is activated by lipin-1-derived DAG during LPS activation, and that blockade of TRPC3 activity ameliorates LPS-driven inflammation and sepsis development in animal models." (PMID 34757442, 2021). "Also, due to the recent development of photopharmacology and optochemical genetics of TRPC3 that could be the foundation for novel therapeutics, these discoveries highlight pharmacological targeting of TRPC3 as an attractive new strategy for the treatment of sepsis and inflammatory diseases." (PMID 34757442, 2021).
Stroke (4 papers, 2020 to 2025). Sudden impairment of blood flow to a part of the brain due to occlusion or rupture of an artery to the brain. "We also identified that ibudilast, an anti-inflammatory drug used in the treatment of asthma and stroke, has the potency to inhibit TRPC3-Nox2 protein complex formation." (PMID 36613540, 2022).
Atrophy (3 papers, 2019 to 2023). Any weakening or degeneration, especially through lack of use. "Myocardial atrophy caused by DOX is also reported to beunder the control of the transient receptor potential canonical 3 (TRPC3)-NOX2complex." (PMID 39076437, 2023). "This ATP-mediated formation of TRPC3-Nox2 complex was also pathophysiologically involved in nutritional deficiency-induced NRCM atrophy." (PMID 31278358, 2019). "Formation of the TRPC3-Nox2 complex amplifies ROS production and results in cardiac atrophy." (PMID 35111832, 2021). "The amplification of NOX2-mediated ROS signaling in cardiomyocytes canbe inhibited by blocking TRPC3, thereby avoiding DOX-induced cardiac atrophy." (PMID 39076437, 2023).
fibrosis (3 papers, 2017 to 2020). the formation of excess fibrous connective tissue in an organ or tissue in a reparative or reactive process. "We have shown that TRPC3 specifically couples to Nox2 to evoke aberrant ROS production, which leads to both cardiac fibrosis and cardiac atrophy." (PMID 32079284, 2020). "We previously reported that transient receptor potential canonical 3 (TRPC3) channel mediates pressure overload-induced maladaptive cardiac fibrosis by forming stably functional complex with NADPH oxidase 2 (Nox2)." (PMID 28790356, 2017).
Hyperglycemia (3 papers, 2017 to 2024). An increased concentration of glucose in the blood. "On the other hand, the upregulation of the TRPC6 protein destabilizes the TRPC3-Nox2 complex and prevents hyperglycemia-induced ROS generation-dependent cardiac dysfunction." (PMID 38397074, 2024). "Upregulation of TRPC6 protein destabilizes the TRPC3-Nox2 complex, which leads to prevention of ROS production-dependent cardiac dysfunction induced by hyperglycemia." (PMID 28790356, 2017). "Hyperglycemia induced by STZ significantly increased mRNA expression level of TRPC6, but not that of TRPC3, in mouse heart." (PMID 28790356, 2017).
muscular dystrophy (3 papers, 2011 to 2021). Muscular dystrophy (MD) refers to a group of more than 30 genetic diseases characterized by progressive weakness and degeneration of the skeletal muscles that control movement. "This is reinforced by the noteworthy work published by Millay and colleagues in 2009, showing that overexpression of TRPC3 specifically in skeletal muscle induced muscular dystrophy in WT mouse." (PMID 34930315, 2021). "In fact, the overexpression of dominant-negative TRPC3 or TRPV2 channels in muscle ameliorates pathological changes, and TRPC3 overexpression in WT mice is sufficient to induce muscular dystrophy." (PMID 21995957, 2011). "Considering that the rAAV-MD based treatments of DMD are currently promising but would rather lead to a milder BMD-like muscular dystrophy, we evaluated the potential of TRPC1 and TRPC3 to represent alternative or complementary therapeutic targets to rAAV-MD based treatments of DMD." (PMID 34930315, 2021).
myocardial infarction (3 papers, 2017 to 2023). Gross necrosis of the myocardium, as a result of interruption of the blood supply to the area, as in coronary thrombosis. "The involvement of TRPC3 was also demonstrated in cardiac remodeling by myocardial infarction (MI) and arrhythmia." (PMID 28936433, 2017).
nephrocalcinosis (3 papers, 2019 to 2021). Nephrocalcinosis is a disorder that occurs when too much calcium is deposited in the kidneys. "Thus, it is possible that an AVP-induced TRPC3 translocation would augment CD Ca2+ reabsorption to decrease a risk of nephrocalcinosis and urolithiasis by preventing Ca2+ precipitation in the luminal fluid during robust water reabsorption in the CD." (PMID 31851715, 2019).
chronic heart failure (2 papers, 2016 to 2019). "Therefore, tuning of TRPC3-Nox2 stability by disrupting TRPC3-Nox2 interaction will be a new therapeutic strategy to improve chronic heart failure." (PMID 27833156, 2016). "It is plausible to speculate that TRPC3 inhibition might be instrumental in blocking excessive renal water retention during the clinically relevant states associated high AVP levels, such as congestive heart failure or syndrome of inappropriate AVP secretion." (PMID 31851715, 2019).
colitis (2 papers, 2024 to 2025). Inflammation of the colon. "The search terms used were "Transient Receptor Potential Channels", "TRP channels", "TRPV1", "TRPA1", "TRPV4", "TRPV2", "TRPM2", "TRPM3", "TRPM7", "TRPM8", "TRPC3", "colitis", "inflammatory bowel disease", "IBD", "ulcerative colitis", "Crohn Disease"." (PMID 41096659, 2025). "We found that TRPC3 is not directly associated with the development of colitis." (PMID 38397074, 2024). "Systemic TRPC3 knockout (KO) and TRPC6 KO mice were treated with dextran sulfate sodium (DSS) to induce colitis." (PMID 38397074, 2024). "To determine whether TRPC6-mediated Zn2+ affects the development of intestinal inflammation, we conducted experiments using whole-body TRPC3 knockout (KO) and TRPC6 KO mice in the DSS-induced colitis model." (PMID 38397074, 2024).
colon cancer (2 papers, 2022 to 2024). "Moreover, high levels of TRPC3 in mesenchymal cells were associated with a worse clinical outcome in colon cancer patients." (PMID 39697630, 2024). "Furthermore, exosomes from colon cancer cells could induce the differentiation of AMSCs into cancer-associated fibroblasts (CAFs) by activating the NF-κB signaling pathway through the transient receptor potential cation channel subfamily C member 3 (TRPC3)." (PMID 39697630, 2024). "Despite the limited number of cases, the data revealed that TRPC3 expression in CAFs was increased in colon cancer tissues at different stages." (PMID 35870973, 2022). "In order to confirm the expression of TRPC3 in the mesenchymal cells from tumor tissue samples, we stained pathological sections of colon cancer tissue from mice." (PMID 35870973, 2022). "The results obtained from the data available for colon cancer in Oncomine showed that the expression of TRPC3 was positively related with the expression of CAF marker genes (α-SMA and FAP)." (PMID 35870973, 2022). "In the present study, we emphasize the crucial role of TRPC3 channel in the invasion and migration of MT-CAFs and its promoting effect on colon cancer cells." (PMID 35870973, 2022). "Finally, the results indicate TRPC3 may be a novel prognostic biomarker and a potential therapeutic target for the treatment of colon cancer." (PMID 35870973, 2022). "In addition, the Oncomine and GEPIA databases showed that TRPC3 expression is higher in colon cancer tissues compared with normal colon tissues, and was positively correlated with the expression of the CAF genes alpha-smooth muscle (α-SMA/ACTA2) and fibroblast activation protein Alpha." (PMID 35870973, 2022). "Using this induced CAF model, we screened out the TRPC3 gene expressed in CAFs as a biomarker, and confirmed that it influences the invasion and migration ability of cancer cells, promoting the progression of colon cancer by activating the NF-κB signaling pathway." (PMID 35870973, 2022). "Therefore, TRPC3 may be a novel therapeutic target for the treatment of colon cancer." (PMID 35870973, 2022).
colorectal cancer (2 papers, 2018 to 2022). A primary or metastatic malignant neoplasm that affects the colon or rectum. "To further verify the expression of TRPC3 in CAFs from colorectal cancer patients and its correlation with the prognosis, we used IHC to detect the expression of TRPC3 in clinical specimens." (PMID 35870973, 2022). "Examination of clinical colorectal cancer specimens confirmed that the expression of TRPC3 in tumors, and especially in CAFs, was closely related with a poor prognosis." (PMID 35870973, 2022). "We found that TRPC3 expression in colorectal cancer tissues was higher than in normal colon tissues." (PMID 35870973, 2022). "The results indicate that TRPC3 may be a potential new therapeutic target for the treatment of colorectal cancer." (PMID 35870973, 2022). "Furthermore, we investigated the expression of TRPC3 in samples from 63 colorectal cancer patients by IHC." (PMID 35870973, 2022). "The result showed that CAFs in colorectal cancer tissues co-expressed TRPC3 and ACTA2." (PMID 35870973, 2022). "To further verify the relationship between TRPC3 and CAFs, we detected the expression of TRPC3 and ACTA2 in clinical specimens of colorectal cancer patients." (PMID 35870973, 2022).
depression (2 papers, 2018 to 2023). "This hypothesis would also provide an explanation for the effects of TRPC3 knockout on CBF changes elicited via cortical spreading depression associated with high NMDA treatment." (PMID 37628789, 2023). "This remarkable consistency strongly suggests that TRPC3 channels are an important contributor to hemodynamic responses to cortical spreading depression." (PMID 37628789, 2023). "Qin and his colleagues showed a complete difference between the depression animal model group and the control group related to the expression level of TRPC3/5 and the morphology in neurons, located in the hippocampus." (PMID 30618863, 2018). "A comparison of TRPC3 knockout mice to controls revealed that the genetic ablation of TRPC3 expression significantly altered the hemodynamic responses elicited using cortical spreading depression and promoted hyperemia consistently." (PMID 37628789, 2023). "There are multiple possible signaling pathways that could lead to the activation of TRPC3 channels by cortical spreading depression." (PMID 37628789, 2023). "Our data showed that the genetic ablation of TRPC3 channel expression significantly changed hemodynamic responses to cortical spreading depression regardless of the experimental approach used to induce it." (PMID 37628789, 2023).
endothelial dysfunction (2 papers, 2017 to 2026). In vascular diseases, endothelial dysfunction is a systemic pathological state of the endothelium (the inner lining of blood vessels) and can be broadly defined as an imbalance between vasodilating and vasoconstricting substances produced by (or acting on) the endothelium. "Altered expression and/or activity of TRPC3 have been associated, directly or indirectly, with endothelial dysfunction and endothelium-related vascular disease." (PMID 28724979, 2017). "Inhibition of TRPC3 channels contributes to H-R-induced suppression of IKCa and SKCa channel activity, which serves as a mechanism underlying endothelial dysfunction under H-R condition and renders TRPC3 channels a potential target for endothelial protection in ischemic status." (PMID 28724979, 2017). "We hypothesize that TRPC1, TRPC3, TRPC4, and TRPC6 act as critical molecular effectors mediating hypoxia-driven calcium influx and downstream signaling pathways that lead to pulmonary vascular remodeling, endothelial dysfunction, and increased pulmonary arterial pressure." (PMID 41751997, 2026).
glomerular diseases (2 papers, 2019 to 2022). "Other members of the TRPC family have effects on glomerular diseases, such as TRPC5 and TRPC3." (PMID 35991898, 2022). "An important observation was that TRPC3 is upregulated in glomerular diseases in a fashion similar to TRPC6, with no change in expression of TRPC5." (PMID 31877991, 2019).
Glucose intolerance (2 papers, 2023 to 2025). Glucose intolerance (GI) can be defined as dysglycemia that comprises both prediabetes and diabetes. "TRPC3 pharmacologic inhibition and knockout in mice lead to defective insulin secretion and glucose intolerance." (PMID 36642838, 2023). "Inhibition of TRPC3, whether through pharmacologic inhibition or knockout, results in decreased insulin secretion and glucose intolerance in mice." (PMID 40316897, 2025).
Hypercalcemia (2 papers, 2019 to 2020). An abnormally increased calcium concentration in the blood. "Another indication on the possible role of this channel in pathophysiology comes from a case report where TRPC3 expression was found to be upregulated in a patient with Williams–Beuren syndrome, a rare neurodevelopmental disorder also associated with hypercalcemia." (PMID 32812807, 2020). "Consistently, the Williams-Beuren syndrome (WBS), a neurodevelopmental disorder commonly associated with hypercalcemia of unknown origin, has been recently linked to upregulation of TRPC3 expression due to deletion of the gene encoding the transcription factor TFII-I." (PMID 31851715, 2019).
itch (2 papers, 2019 to 2023). "In this review, we discuss the role of TRP channels TRPA1, TRPV1, TRPV2, TRPV3, TRPV4, TRPM8, and TRPC3/4 in acute and chronic pruritus." (PMID 38139833, 2023).
lung adenocarcinoma (2 papers, 2019 to 2023). A carcinoma that arises from the lung and is characterized by the presence of malignant glandular epithelial cells. "This study implies both the diagnostic and prognostic value of TRPC3 immunohistochemistry in the work-up of suspected lung adenocarcinoma." (PMID 37240443, 2023). "By contrast, in a cohort of 95 patients with lung adenocarcinoma, TRPC3 expression as determined by mRNA levels (real-time RT-PCR) identified a group with good prognosis." (PMID 37240443, 2023).
neuroblastoma (2 papers, 2022). Neuroblastoma (NB) is the most common solid, extracranial childhood tumor. "Interestingly, another set of observations in CHO, HEK-293, and human neuroblastoma SH-5Y5Y cells indicates that PKCγ can regulate Ca2+ influx through modulating the plasma membrane TRPC3 channels." (PMID 35265671, 2022).
pancreatitis (2 papers, 2013 to 2017). Inflammation of the pancreas. "Our findings could point to a role of TRPC3 channels in pancreatitis." (PMID 27903970, 2017). "For example, mice deficient in the transient receptor potential cation channel, subfamily C, member 3, (TRPC3), a SOC, have reduced calcium elevations in secretagogue, bile acid, and alcohol metabolite-mediated models of pancreatitis." (PMID 24474939, 2013).
Parkinson disease (2 papers, 2020). A progressive degenerative disorder of the central nervous system characterized by loss of dopamine producing neurons in the substantia nigra and the presence of Lewy bodies in the substantia nigra and locus coeruleus. "Inhibition of TRPC3 was shown to depolarize GABA neurons in the substantia nigra pars reticulate (SNpr), which are associated with parkinsonism." (PMID 32351395, 2020). "Thus, the link of TRPC3 expression and function in mitochondria to α-synuclein upregulation implicates a role of TRPC3 in the pathogenesis of Parkinson’s disease." (PMID 33490083, 2020).
renal carcinoma (2 papers, 2022 to 2025). A carcinoma arising from the epithelium of the renal parenchyma or the renal pelvis. "Indeed, in our experiments, AC1903 inhibited multiple TRPC channels including TRPC3, TRPC4, TRPC5, TRPC6, TRPC4–C1, and TRPC5–C1, as well as endogenous TRPC1:C4 channels in A498 renal cancer cells, all with low micromolar IC50 values (1.8–18 μM)." (PMID 34999117, 2022).
salivary gland stones (2 papers, 2020 to 2023). "Significantly, we found that TRPC3 was expressed in mice and human salivary ductal cells, while intraductal stones were detected in both mice (TRPC3−/−) and patient (sialolithiasis) salivary glands." (PMID 37031239, 2023). "To further establish the role of TRPC3 in sialolithiasis, we compared the presence of CaSR and TRPC3 in human (non-stone) control and stone patient SMG tissue sections." (PMID 37031239, 2023).
urinary stone (2 papers, 2019 to 2021). "Altogether, the pH-induced alteration of the Ca2+ signaling signature in PT cells from TRPC3 ablated mice exacerbated the pathophysiology of mixed urinary stone formation, which may aid in uncovering the downstream mechanism of CaNL." (PMID 33802660, 2021).
Williams-Beuren syndrome (2 papers, 2019 to 2020). "Interestingly, hypercalcemia in the Williams-Beuren syndrome (WBS) has been associated with augmented TRPC3 expression in both collecting duct and intestinal epithelium due to mutation in the transcription factor TFII-I." (PMID 32787494, 2020).
acute pancreatitis (1 paper, 2017). An acute inflammatory process that leads to necrosis of the pancreatic parenchyma. "The attenuation of an acute pancreatitis in TRPC3−/− animals was explained on the basis of an altered exocytotic protease secretion from acinar cells." (PMID 27903970, 2017). "Since PSCs also become activated in an acute pancreatitis our findings raise the possibility that a diminished activation of PSCs might have also contributed to the attenuated acute pancreatitis in TRPC3−/− mice." (PMID 27903970, 2017).
acute pneumonia (1 paper, 2024). "Activation of TRPC3/6 promotes the loss of endothelial barrier function in acute pneumonia, but TRPC3/6‐mediated signaling pathways may also be important for maintaining endothelial barrier integrity." (PMID 40625902, 2024).